SMARCB1 (SWI/SNF related BAF chromatin remodeling complex subunit B1)
Diseases named in the same sentence as SMARCB1 in open-access papers (continued):
Sharing a sentence is not in itself a finding about the gene and the disease.
rhabdoid tumor (continued). "Malignant rhabdoid tumors, including AT/RTs, are characterized by genetic alterations affecting the SMARCB1 (also known as hSNF5 and INI1) locus in chromosome 22q11.2 or, rarely, the SMARCA4 locus in chromosome 19p13.2." (PMID 31462227, 2019). "Atypical teratoid/rhabdoid tumors (AT/RTs) are highly malignant brain tumors with inactivation of the SMARCB1 gene, which play a critical role in genomic transcriptional control." (PMID 31462227, 2019). "High-resolution genomic analysis and whole exome sequencing studies identified extremely low mutation rates for genes other than the biallelic inactivation of SMARCB1 in rhabdoid tumors." (PMID 31462227, 2019). "Historically, the first evidence for a link between the mSWI/SNF complexes and cancer was shown in Malignant Rhabdoid Tumors (MRT), with the hallmark biallelic inactivation of SMARCB1, the gene coding for the BAF47 protein, observed in 98% of tumors." (PMID 31681608, 2019). "Immunohistochemical staining revealed the complete loss of SMARCB1 expression in the pRCC1 as observed in malignant rhabdoid tumours with biallelic SMARCB1 inactivation." (PMID 27921248, 2017). "Alterations in this gene, or the related SWI/SNF chromatin remodeling gene SMARCB1, have been previously reported in atypical teratoid/rhabdoid tumors (ATRTs) and malignant rhabdoid tumors (MRTs)." (PMID 26646792, 2016). "The BAF47 (INI1; SMARCB1; SNF5) subunit was the first to be implicated as a critical tumor suppressor gene whose loss underlies the genesis of malignant rhabdoid tumors." (PMID 28105457, 2016). "SMARCB1, a core subunit of the SWI/SNF complex, is a known tumor suppressor and its loss was associated with rhabdoid tumor onset." (PMID 26544626, 2015). "SMARCB1 is known to be disrupted in malignant rhabdoid tumors, round cell soft-tissue sarcomas (most were a subset of tumors resembling extraskeletal myxoid chondrosarcoma with rhabdoid features, epithelioid sarcomas, and schwannomatosis." (PMID 24983247, 2014). "Pharmacological inhibition of EZH2 by using a new EZH2 inhibitor has been recently shown to induce anti-tumoral effects in malignant rhabdoid tumor (MRT) cells deleted for SMARCB1." (PMID 24575771, 2014). "Initial insights into the role of the SWI/SNF complex in tumorigenesis arose from the identification of the core subunit SMARCB1/SNF5 in malignant rhabdoid tumors, following demonstration of its tumor suppressor function in cell lines and animal models." (PMID 25391308, 2014). "INI-1 is the protein product of the hSNF5/INI1/SMARCB1/BAF47 gene as a tumor suppressor gene located on 22q11.2 that is characteristically inactivated in malignant rhabdoid tumor (MRT) of infancy." (PMID 23915498, 2013). "The differential diagnosis is with the malignant rhabdoid tumors of infancy characterized by genetic inactivation of SMARCB1 (INI1) or deletions of chromosome 22q12 locus." (PMID 23425390, 2013). "SMARCB1 is deleted in rhabdoid tumor, an aggressive paediatric malignancy affecting the kidney and CNS." (PMID 19221586, 2009). "In rhabdoid tumors, the loss of SMARCB1 does not interfere with the non-canonical BAF (ncBAF) complex, which requires a functional ATPase subunit." (PMID 39906560, 2025). "Though the INI1-deficient malignant rhabdoid tumor can co-occur with AT/RT in the context of rhabdoid tumor predisposition syndrome in patients with SMARCB1 germ line variant RPTS1, RMC has never been reported to co-occur with AT/RT." (PMID 39833894, 2025). "Initial preclinical studies demonstrated that it induced apoptosis and differentiation in SMARCB1-deleted rhabdoid tumors in vitro and in vivo, with significant anti-tumor activity observed in rhabdoid tumor models, including AT/RT, but variable responses across other pediatric solid tumors." (PMID 40556679, 2025). "The unique activity of super-enhancers (SEs) has been implicated in SWI/SNF-mutant rhabdoid tumors, where SMARCB1-deficient SWI/SNF complex remains localized to SEs but not regular enhancers." (PMID 39906560, 2025).
rhabdoid tumor (continued). "Importantly, in SMARCB1-null rhabdoid cancer cells, super-enhancers are both bound by remaining SWI/SNF subunits and are essential for rhabdoid tumor cell survival." (PMID 38473277, 2024). "Recently, in our study of a kidney-derived SMARCB1-null rhabdoid cancer cell line, we reported that BRG1, a synthetic lethal target in rhabdoid cancer cells, actively remodels chromatin at select enhancer regions, and that this remodeling profoundly influences gene expression." (PMID 38473277, 2024). "However, studies on the effect of malignant rhabdoid tumors and synovial sarcoma with a deficit of SMARCB1 were limited." (PMID 39398818, 2024). "A rare subset of pediatric solid tumors including malignant rhabdoid tumors, chordomas and epithelioid sarcoma which typically have low TMB, outlier high immune infiltration and mutations affecting the SWI/SNF complex (SMARCB1/A4), have been among rare responders to ICI33." (PMID 38755180, 2024). "SMARCB1 is also lost in a variety of other pediatric cancers, arising in the same organs as rhabdoid tumors, such as cribriform neuroepithelial tumors in the brain or renal medullary carcinoma in the kidney, or arising in other locations such as synovial sarcomas." (PMID 39542244, 2024). "Rhabdoid tumors, characterized and driven by the loss of the mammalian SWItch/sucrose nonfermentable subunit SMARCB1, are very aggressive childhood cancers that can arise in the brain, the kidney, or soft tissues." (PMID 39542244, 2024). "Transcriptome analyses aligned SMARCA4‐UTs more closely with SMARCA4‐mutated SCCOHTs and SMARCB1‐inactivated malignant rhabdoid tumors (MRTs) rather than conventional NSCLCs." (PMID 38124509, 2023). "When rhabdoid tumors are correctly diagnosed with testing for loss of SMARCB1, neither hepatoblastoma with small cell undifferentiated component nor alpha-fetoprotein less than 100 ng/mL confer poor prognosis." (PMID 36672416, 2023). "In addition, it is known that SMARCB1-mutant rhabdoid tumors detect infiltration by subpopulations of T cells, which indicates a tumor-specific immune response." (PMID 37175555, 2023). "Forty-one patients were diagnosed with HB with SCU component and not classified as rhabdoid tumors, and none had documented loss of SMARCB1 expression by INI1 immunohistochemistry." (PMID 36672416, 2023). "SMARCB1 tumors have been found in various locations, including the sinonasal region, gastrointestinal tract, central nervous system (in atypical teratoid and rhabdoid tumors), and perirenal region (in malignant rhabdoid tumors) in both adults and children." (PMID 37974295, 2023). "TILs therapy may represent a novel approach for rhabdoid tumors, as TILs could recognize specific aberrations in SWI/SNFc, such as complete loss of SMARCA4 or SMARCB1 or other neoantigens created by epigenetic changes occurring within the tumor." (PMID 37446319, 2023). "Moreover, suppression of EZH2 is proposed as a therapeutic strategy for both SMARCB1 mutant rhabdoid tumors and H3K27M gliomas (20, 21, 29, –31)." (PMID 37094128, 2023). "Similar to other rhabdoid tumors, SCCOHT may also harbor SWI/SNF core subunit SMARCB1 (also known as INI1/SNF5/BAF47) mutations instead of SMARCA4." (PMID 36430148, 2022). "We generated methylation profiles of seven RMC samples and compared the hitherto unexplored methylation landscape of these tumors to other renal tumors and malignant rhabdoid tumors as well as epithelioid sarcomas, constituting two prototypically SMARCB1 aberrant entities." (PMID 36291828, 2022). "The loss of SMARCB1, another main ubiquitous and constant subunit protein of the SWI/SNF complexes, has also been described as a key genetic event in various tumor types, including malignant rhabdoid tumors." (PMID 35326637, 2022).
rhabdoid tumor (continued). "In particular, SMARCB1 is involved in ES, but also in malignant rhabdoid tumors (MRT), atypical teratoid/rhabdoid tumors (AT/RT) of the central nervous system, malignant peripheral nerve sheath tumors (MPNST), myoepithelial neoplasms and renal medullary carcinomas (RMC)." (PMID 36078034, 2022). "While these findings confirm the developmental origin of rhabdoid tumors, it fails to elucidate how SMARCB1-deficient cancers arise in adults." (PMID 35892904, 2022). "Alternatively, certain NRSTS may be part of the diagnostic criteria for a given disorder (e.g., rhabdoid tumors in rhabdoid tumor predisposition syndrome, due to SMARCB1/INI1 mutation)." (PMID 35053663, 2022). "In addition, the biallelically inactivated SMARCB1 was frequently found in malignant rhabdoid tumors, which is a clear evidence that at least one SWI/SNF subunit is indeed a tumor suppressor." (PMID 36371186, 2022). "The first example of the link between SWI/SNF chromatin remodelers and cancer development was the fact that 100% of malignant rhabdoid tumors (MRTs), a particularly aggressive type of childhood cancer, were found to carry mutations in the SMARCB1 gene (BAF47 protein)." (PMID 36605718, 2022). "Rhabdoid tumors (RTs) are malignant tumors driven by inactivation of the SWI/SNF subunit SMARCB1." (PMID 35928964, 2022). "Poorly differentiated chordomas are characterized by the loss of INI1/SMARCB1 and may also represent a discrete entity with a more aggressive phenotype, which is more similar to rhabdoid tumors." (PMID 36465398, 2022). "Inactivation of biallelic SMARCB1/SNF5 is largely restricted to the rare pediatric rhabdoid tumors." (PMID 33419967, 2021). "In addition, tazemetostat has been tested in solid tumors with notable preclinical activity in pediatric malignant rhabdoid tumors, which harbor inactivating biallelic mutations in the SWI/SNF subunit SMARCB1 as well as SMARCB1-deificent synovial sarcoma." (PMID 34671561, 2021). "We show that they form a separate group segregating from SMARCB1 mutated ATRTs and from other SMARCA4-deficient tumors like small cell carcinoma of the ovary, hypercalcemic type (SCCOHT) or SMARCA4 mutated extra-cranial malignant rhabdoid tumors." (PMID 33331994, 2021). "Gene fusions of PLAGL1 with EWSR1 have been reported exceptionally rarely in neoplasms of the CNS, including single cases of a SMARCB1-deficient atypical teratoid/rhabdoid tumor (AT/RT) and a glioneuronal tumor, not elsewhere classified (NEC)." (PMID 34355256, 2021). "Malignant rhabdoid tumors are associated with germline mutations of SMARCB1 or SMARCA4, whereas no SMARCA4 germline mutations have been reported in SMARCA4-deficient thoracic sarcomas." (PMID 34131151, 2021). "In order to exclude an atypical teratoid rhabdoid tumor, antibody for INI-1 was performed and showed nuclear retention (no mutation on SMARCB1 gene)." (PMID 34906194, 2021). "Interestingly, SMARCB1-mutant rhabdoid tumors and SMARCA4-mutant small cell carcinoma of the ovary have an immune active microenvironment and are responsive to immune-checkpoint inhibition." (PMID 34359794, 2021). "Early investigations of malignant rhabdoid tumors showed that re-expression of SMARCB1 led to activation of transcription initiation either by recruitment of BAF complexes or activation of existing ones, implying that oncogenesis in the context of SMARCB1 loss is due to promoter pausing." (PMID 34071089, 2021). "Even though previous studies have demonstrated that the majority of rhabdoid tumors arise as a consequence of homozygous inactivation of the SMARCB1 (INI1/SNF5/BAF47) gene, potential biomarkers to predict the prognostic outcomes in children with RTK have rarely been identified." (PMID 32908900, 2020). "The loss of function of the SMARCB1 (INI1/SNF5/BAF47) gene is the common genetic abnormality in rhabdoid tumors, regardless of the anatomic origin." (PMID 32908900, 2020).
rhabdoid tumor (continued). "In addition, loss of specific gene components of the SWI/SNF chromatin-remodeling complex such as SMARCB1 or SMARCA4 characterizes rhabdoid sarcomas, another type of pediatric STS." (PMID 32232030, 2020). "Conversely, BAF47 appeared not needed for the proliferative arrest, as reported in rhabdoid tumors with loss of SMARCB1 (as reviewed by Kohashi and Oda, 2017), observed after SS18-SSX depletion." (PMID 32232030, 2020). "Restoration of SMARCB1 induced cellular senescence in rhabdoid cancer cell lines." (PMID 31462227, 2019). "Analyses of such mutations suggest that they do not result in a complete loss of the protein as in rhabdoid tumors but in reduced SMARCB1 gene expression." (PMID 31273213, 2019). "For instance, SMARCB1 (INI1/SNF5/BAF47) is a subunit of the SWI/SNF complex that is lost in nearly all rhabdoid tumors, creating an oncogenic dependency on the PRC2-EZH2 methyltransferase, and sensitizing these tumors to small molecule inhibitors of EZH2 both in vitro and in vivo." (PMID 27391784, 2016). "Consistent with the role of a tumor suppressor gene, biallelic inactivation of SMARCB1 is present in rhabdoid tumors, and ATRTs may occur sporadically or in the setting of a rhabdoid predisposition syndrome 5,6." (PMID 24402832, 2014). "In addition, deletion of the INI1 (SMARCB1 or hSNF5) subunit of the SWI/SNF chromatin-remodeling complex occurs in nearly all malignant rhabdoid tumors (MRTs), a childhood cancer with a particularly poor prognosis." (PMID 24157419, 2013). "The main differential diagnosis is with the malignant rhabdoid tumors (MRTs), a neoplasm more common in childhood characterized by genetic inactivation of SMARCB1 (SNF5, INI-1), a component of the SWI/SNF chromatin remodelling complex or deletions at chromosome 22q." (PMID 23425390, 2013). "While we did not identify any rhabdoid tumor cases with germline SMARCB1 mutation in our small series, germ-line predisposition has now been reported in a sufficient number of cases of both rhabdoid tumor and schwannomatosis to warrant routine investigation." (PMID 20003390, 2009). "Having previously demonstrated the presence of mSWI/SNF subunits (including SMARCB1) in the cytoplasm of other cell lines and their interaction with the translation machinery, we wanted to assess whether SMARCB1 would localize in the cytoplasm in rhabdoid tumor cell lines as well." (PMID 39542244, 2024). "Although SMARCB1 is not frequently mutated in melanoma, inactivating mutations in SMARCB1 frequently occur in a number of other cancers, especially in pediatric rhabdoid tumors, where there is frequent biallelic SMARCB1 disruption." (PMID 35323214, 2022). "The diagnosis of RTPS is established in a proband with a rhabdoid tumor and/or a family history of RT and/or multiple SMARCB1/SMARCA4 deficient tumors (synchronous or metachronous) and identification of a germline pathogenic variant in SMARCB1 or SMARCA4 by genetic testing." (PMID 33692948, 2021). "In addition, several infant or pediatric malignancies appear to be due to a single genetic event: MLL-AF4 fusion in infant acute lymphoblastic leukemia, homozygous inactivation of SMARCB1 in pediatric rhabdoid tumors, and C11orf95-RELA fusion in brain ependymoma." (PMID 27494029, 2016). "Significantly, we report for the first time, parallels between the molecular pathways of SMARCB1 restoration and Romidepsin treatment, and demonstrate a biological basis for the further exploration of histone deacetylase inhibitors as relevant therapeutic reagents in the treatment of rhabdoid tumor." (PMID 19221586, 2009).
rhabdoid tumor (continued). "These cell lines, derived from rhabdoid tumors of different origin (brain, BT12 and BT16; kidney, G401; and liver, TTC549), were modified to conditionally express SMARCB1 in the presence of doxycycline." (PMID 39542244, 2024). "In this context, the relationship between the tumour suppressor SNF5 (SMARCB1) and GLI1 in malignant rhabdoid tumours is particularly suggestive, as about 25% of RMS tumours share the SNF5 mutational inactivation characteristic of rhabdoid tumours." (PMID 36765685, 2023). "Several human SWI/SNF subunits have been shown to be involved in cancer, with mutations in some being strongly correlated with specific malignancies, such as is the case with INI1/SMARCB1/SNF5 and rhabdoid tumors." (PMID 37650639, 2023). "SMARCB1 is a member of the SWI/SNF chromatin-remodeling complex and functions as a tumor suppressor in most rhabdoid tumors." (PMID 35159116, 2022). "This is well exemplified by the highly aggressive malignant rhabdoid tumor (MRT), where the only gene classically showing recurrent inactivation is SMARCB1, a subunit member of the BAF chromatin-remodeling complex." (PMID 34071089, 2021). "Alterations in the chromatin-remodeling complexes of the SWI/SNF family (BAF, PBAF), particularly in the subunits SMARCB1 (INI1) and SMARCA4, are the primary driver event for rhabdoid tumor development." (PMID 34830753, 2021). "Experimental rhabdoid tumor models have demonstrated significant regression of established tumors under ICB therapy, up to 67% of the mice with the SMARCB1-mutant rhabdomyoma readily responded to anti-PD-1 treatment." (PMID 33419967, 2021). "Although molecular genetic studies of rhabdoid tumors typically reveal the biallelic inactivation of the SMARCB1 gene, other tumor types (schwannomas, meningiomas) may also show deletions or mutations of the SMARCB1 gene that lead to a loss of INI1 protein expression." (PMID 31835848, 2019). "We show that PDGFRα levels are regulated by SMARCB1 expression, and assessment of clinical specimens documents the expression of both PDGFRα and FGFR1 in rhabdoid tumor patients." (PMID 27783942, 2016). "The most compelling case has been that of SMARCB1 (SNF5), which was discovered to be homozygously inactivated in nearly all rhabdoid tumors (a rare pediatric malignancy)." (PMID 23355908, 2013). "Cyclin E can overcome SMARCB1 induced proliferation arrest in RT cell lines also implying involvement of CIP KIP inhibitors in rhabdoid tumor, however in other studies CDKN1A and CDKN1B expression were unchanged by SMARCB1 expression." (PMID 19221586, 2009). "TfRscFv enables the efficient delivery of a plasmid containing the human wild-type SMARCB1 gene to tumor cells.The scL-SMARCB1 nanocomplex restores SMARCB1 expression, which in turn inhibits the proliferation of ATRT (atypical teratoid/rhabdoid tumor) cells and induces senescence and apoptosis." (PMID 40115023, 2025). "A similar pattern, with typical enhancers but not SEs being affected, has been observed in SMARCB1-defectient rhabdoid tumors, in which mSWI/SNF stability is compromised." (PMID 40846763, 2025). "While these tumors differ in their methylation pattern from their SMARCB1 deleted counterparts, heterozygous aberrations in SMARCA4 so far have not been implicated in the biology of rhabdoid tumors." (PMID 41168858, 2025). "For further experiments, we selected SAHA (suberoylanilide hydroxamic acid/vorinostat) because it is FDA-approved and has been shown to be an effective agent in Smarcb1-negative rhabdoid tumors in our previous studies." (PMID 39362842, 2024). "Although SMARCB1/INI1 is widely used as a marker of rhabdoid tumors, its relevance has not yet been comprehensively investigated in RCTs." (PMID 37239344, 2023).